BLNK (B cell linker)
Diseases named in the same sentence as BLNK in open-access papers (continued):
Sharing a sentence is not in itself a finding about the gene and the disease.
malaria (1 paper, 2018). Malaria is a serious and sometimes fatal disease caused by a parasite that commonly infects a certain type of mosquito which feeds on humans. "Transcriptional expression also increased in both TNT and malaria exposures for immune responses, including increased expression for B-cell linker protein (NP_990, 239.1), a functional component of B-cell activation." (PMID 30518325, 2018).
metastatic cancer (1 paper, 2023). A carcinoma which has spread from the original site of growth to another anatomic site. "BLNK expression was equal in metastatic cancer tissues when compared to the control tissue." (PMID 37869102, 2023).
renal cell carcinoma (1 paper, 2023). "According to CTRP drug sensitivity analysis, high level of CBX2, BLNK, PLK4, STIL and BIRC5 were associated with increased sensitivity to inhibitors of VEGF and MET pathways, which happened to be two crucial driver pathways of renal cell carcinoma." (PMID 37917664, 2023).
tongue squamous cell carcinoma (1 paper, 2023). A squamous cell carcinoma that arises from the tongue. "Eight genes were shown to be related to the prognosis in patients with tongue squamous cell carcinoma (AXL, SCG5, VOPP1, DCBLD2, DRAM, DUSP1, AQP5, BLNK)." (PMID 37925175, 2023).
tumor (13 papers, 2010 to 2025). "We also found a correlation between HOXB9 expression and tumor size (p = 0.021) and gender (p = 0.006), BLNK and perineural invasion (p = 0.023) and ZNF813 and perineural invasion (p = 0.029)." (PMID 26041877, 2015). "BLNK is a tumor suppressor that regulates IL-7-dependent survival of pre-B cells via direct inhibition of JAK3, indicating a crucial role of JAK3 in pre-B cell proliferation." (PMID 20149240, 2010). "In fact, BLNK is considered an initiator of critical tumor suppressors." (PMID 37925175, 2023). "Since tumor cells tend to grow under metabolic stress in vivo, we tested whether BLNK inhibits 3D growth of BT474T cells under such stress and found that this the case." (PMID 35933456, 2022). "Additional support for an involvement of the BCR pathway in the pathogenesis of WM came from observations that a number of BCR signaling molecules, including SFK, SYK, BTK, BLNK, PLCγ2, ERK, AKT, and NF-κΒ, are constitutively activated in primary WM tumor cells." (PMID 32481736, 2020). "Additional evidence for a potential role of the BCR pathway in the pathogenesis of MCL was provided by phospho-proteomic analysis of MCL cell lines and primary tumor samples demonstrating constitutive activation of multiple BCR signaling molecules, including CD79B, LYN, SYK, BLNK, BTK, and PLCγ2." (PMID 32481736, 2020). "Interestingly, also a number of oncogenes is up regulated by E2 (MERTK, RET and its ligand ARTN), and several (putative) tumor suppressor genes are down regulated by E2 (BLNK, LATS2, RPRM) that are not, or less, regulated by EGF." (PMID 24758408, 2014).
cancer (10 papers, 2015 to 2025). A tumor composed of atypical neoplastic, often pleomorphic cells that invade other tissues. "The expression of DUSP1, AQP5, and BLNK in malignant tumors of the oral region was significantly lower than in normal tissues, according to the TCGA database." (PMID 37925175, 2023). "ErbB2-induced BLNK downregulation likely blocks the apoptotic form of death of detached cancer cells since we observed that ectopic BLNK triggers apoptosis symptoms in the cells, such as caspase-3 cleavage and Annexin V positivity." (PMID 35933456, 2022). "Notably, seven UReg genes (GALNT14, KIAA0040, EPB41L1, ZNF469, BLNK, AK7, and WSCD1) are associated with the progression of various cancers in humans." (PMID 40241800, 2025). "There was a correlation between RNA-seq and validation cohort for the IL6R, BLNK, and TNFSF10 DEGs when cancer and control tissues were compared." (PMID 37869102, 2023). "High fold change correlation for IL6R, TNFSF10, and BLNK DEGs was found between the matching samples and all CRC tissue samples in cancer vs. control correlation." (PMID 37869102, 2023). "The eight mRNAs selected for further analysis, AXL, SCG5, VOPP1, DCBLD2 and DRAM1 are cancer-promoting genes, DUSP1, AQP5 and BLNK are cancer suppressor genes." (PMID 37925175, 2023). "KRAS-positive tissues revealed weakly significant upregulation of BLNK and downregulation of MICB and TNFSF10 expression when compared to KRAS-negative cancer tissue." (PMID 37869102, 2023). "The results revealed five cancer-promoting genes (AXL, SCG5, VOPP1, DCBLD2, DRAM1), and three tumor suppressor genes (DUSP1, AQP5, BLNK)." (PMID 37925175, 2023). "BLNK expression on a large cohort of CRC patients was found to be significantly lower in the cancer group and equal expression in mCRC when compared to primary cancer and a higher expression in the KRAS-positive group." (PMID 37869102, 2023).
BLNK also shares sentences with these, for which no sentence is quoted: autoimmune disease (3 papers); osteoarthritis (2); prostate carcinoma (2); B-cell acute lymphoblastic leukemia (1); brucellosis (1); B‐cell lymphoma (1); chronic lymphocytic leukemia (1); common variable immunodeficiency (1); diabetes mellitus (1); diffuse large B-cell lymphoma (1); endothelial dysfunction (1); experimental autoimmune encephalomyelitis (1); follicular lymphoma (1); hematological disease (1); hepatocellular carcinoma (1); inborn error of immunity (1); multiple myeloma (1); myelodysplastic syndrome (1); neuroblastoma (1); oral squamous cell carcinoma (1); T-cell LGL leukemia (1); Waldenström’s macroglobulinemia (1).